YAP1 (Yes1 associated transcriptional regulator)
Diseases named in the same sentence as YAP1 in open-access papers (continued):
Sharing a sentence is not in itself a finding about the gene and the disease.
cancer (continued). "We conducted a coexpression analysis of PGC-1α against the four SCNC lineage markers—ASCL1, POU2F3, NEUROD1, and YAP1—across all 1,466 human cancer cell lines from the Cancer Cell Line Encyclopedia (CCLE)." (PMID 39589879, 2024). "YAP1 activity is inhibited by the highly conserved Hippo pathway, which is frequently inactivated in human cancers." (PMID 38496413, 2024). "YAP1 is also activated in cancers via dysregulated signalling of Src family kinases, growth factors, and cytokines." (PMID 37957015, 2024). "As a crucial biomarker of cancers, which is now a hot spot in current research in cancer, the methylation site of YAP1 by SETD7 deserves further investigation." (PMID 38670954, 2024). "YAP1 has emerged as a key oncogene that play a critical role in various aspects of tumorigenesis and cancer progression." (PMID 38967794, 2024). "Strikingly, simultaneous injection of YAP1-Sh cells and WT cancer cells (MB49) in the same mice showed decreased growth of the WT CDX compared with stand-alone WT xenograft grown in separate mice." (PMID 39630608, 2024). "Given recent studies in epithelial tumors showing that Yap1 can influence the cancer cell “secretome”, we measured 31 cytokines and chemokines in sample supernatants from our CART cell cytolysis assays." (PMID 38652549, 2024). "In YK-4C SCC cases, cancer cells often displayed diffuse strong positivity for YAP1 in the nucleus and cytoplasm." (PMID 38444414, 2024). "YAP1 drives cancer stemness in LUAD and UCB, and different reports support that generation of CSCs is the primary step toward immune evasion." (PMID 39630608, 2024). "YAP1 functions as an oncogene; its overexpression inhibits cell contact and promotes cancer cell proliferation and invasion." (PMID 38444414, 2024). "Collectively, the results of the present study indicate that the miRNAs-YAP1/YPEL3 cascade can be activated to protect cancer promotion." (PMID 39345743, 2024). "The recognized oncogenic properties of YAP1 and TAZ have solidified them as primary targets for developing inhibitors to treat cancer and other hyperproliferative diseases, mainly focused on blocking YAP1 and TAZ interaction with TEAD." (PMID 39502361, 2024). "Differently, in PDACs, stress induces the Yap1 and Cox2 signaling circuits via cancer cells interacting with stromal fibroblasts, which requires co-targeting Yap1 in cancer cells and Cox2 in fibroblasts to intervene." (PMID 39468013, 2024). "For instance, transcriptional coactivator YAP1 protein (YAP1) is a known transcription regulator that is heavily involved in the Hippo signaling pathway, particularly during cancer development." (PMID 38866007, 2024). "VGLL4 suppresses the cancerous phenotype of malignant epidermal squamous cell carcinoma by inhibiting YAP1/TEAD-dependent pro-cancer signaling." (PMID 38831454, 2024). "Our data show that fusion-positive ES-2 cancer cells depend on the YM fusion for growth and survival and that the YM fusion drives YAP1-mediated transcription." (PMID 39624057, 2024). "Many cancers, including lung, breast, melanoma, prostate, and colorectal cancer, have widespread YAP1/TAZ activation, and this activation is crucial for the initiation, development, and metastasis of cancer." (PMID 38730733, 2024). "Hippo signaling is one of the top pathways altered in human cancer, and intensive focus has been devoted to developing therapies targeting Hippo-dependent transcription mediated by YAP1 and TAZ interaction with TEAD proteins." (PMID 39502361, 2024). "Although YAP1 functions in both cancer and immune cells are well-established, our study highlights its differential expression and functions in CAF populations." (PMID 38346978, 2024). "More importantly, the PRRG2 overexpression-mediated reduction in cancer cell migration and invasion was profoundly abolished upon concomitant silencing of YAP1, supporting a critical role of YAP1 in PRRG2-mediated metastatic regulation." (PMID 38355937, 2024).
cancer (continued). "Strikingly, 22 of 31 cancer types (70%) in TCGA datasets showed positive correlations (Pearson coefficient r > 0.3) between Yap1 signature (51-gene core signature) and PTGS2 (Cox2) mRNA expression." (PMID 39468013, 2024). "Cooperation between YAP1/TAZ and SRF was reported for the differentiation of vascular SMCs but also in certain cancer cells and cancer-associated fibroblasts." (PMID 39155965, 2024). "To further understand the mechanism of YAP1-associated TIME, we analyzed a panel of 32 cancer-associated cytokines/chemokines on a qPCR array in YAP1-Sh and YAP1 Sh-control MB49 cells and CDXs." (PMID 39630608, 2024). "YAP1 is identified as a cancer oncogene and suggests that YAP1 contributes excessively to the progression of many cancers." (PMID 38730733, 2024). "YAP1 inhibition with ICI should also be done on other YAP1-expressing cancers with poor immunogenic response." (PMID 39630608, 2024). "By integrating single-cell transcriptomic data from PDAC mouse models and clinical pathological information from PDAC patients, we identified Yap1 in cancer cells and Cox2 in stromal fibroblasts as two key nodes in this signaling circuit." (PMID 39468013, 2024). "YAP1-mediated immune-resistance is possibly conferred by increased expression of PD-L1 in other cancers." (PMID 39639369, 2024). "CSN6 promotes HCC cancer cell growth in vitro and in vivo through YAP1 nuclear translocalization and activation." (PMID 38308184, 2024). "Collectively, our results indicate that YAP1 induction led to the expression of various cancer-promoting chemokines/cytokines and these in turn led to induction of an immunosuppressive TME." (PMID 39630608, 2024). "Somatic mutation data in human cancers also argues for the influence of an HPV oncoprotein on Hippo signaling and YAP1." (PMID 38496413, 2024). "We further examined the expression levels of 22 YAP1/WWTR1 signature genes identified in cancers by the previous study." (PMID 38624208, 2024). "As YAP1 localization in the nucleus is key for its interaction with TEAD transcription factors, we next analyzed YAP1 accumulation in nuclei and found that YAP1 nuclear staining was significantly reduced after chemotherapy in stroma and in cancer cells." (PMID 38346978, 2024). "By enhancing the binding of MST2 to LATS1/2, the activity of LATS kinase and the phosphorylation of YAP1 are regulated to inhibit the cancer-promoting effect of YAP1." (PMID 38698812, 2024). "YAP1, a direct binding partner of MYL9 linked to a pro-cancer signaling pathway, is transcriptionally activated when a cell senses a stiff ECM." (PMID 39768172, 2024). "Previous studies have shown that increased NUP37 expression in HCC acts as a positive regulator of Yes-associated protein 1/TEA domain family member (YAP1/TEAD) signaling, thereby promoting cancer progression." (PMID 39080077, 2024). "Somatic mutation data in human cancers also argue for the influence of an HPV oncoprotein on Hippo signaling and YAP1." (PMID 39248565, 2024). "In summary, this study provides insights into YAP1 signaling as a driver for cancer stemness and an inducer of immunosuppressive TIME." (PMID 39630608, 2024). "Our results however revealed that YAP1 is transcriptionally activated through an ITGA5/ITGB1/CREB pathway after interaction with fibroblasts in cancer cells." (PMID 36936987, 2023). "Inhibiting YAP-1 has been shown to reduce cancer cell growth and proliferation, making it a potential target for treating YAP-associated diseases." (PMID 37476371, 2023). "The Hippo pathway has been widely demonstrated to play an important role in cancer, where YAP1, one of the key components of the Hippo pathway, interacts with EMT-related proteins to influence tumors cell migration and invasion." (PMID 37384755, 2023). "Interaction with YAP1 to stabilize ΔNp63 and protect cancer cells from ultraviolet-induced apoptosis." (PMID 37182132, 2023).
cancer (continued). "LIPH catalyzes the conversion of PA to LPA and facilitates cancer cell proliferation by enhancing YAP1 nuclear localization, stimulating the PI3K/AKT/HIF1A pathway, and maintaining ALDOA stability, ultimately resulting in aberrant glycolysis and tumorigenesis." (PMID 37990271, 2023). "Elucidation of cellular and molecular mechanisms by which MUC13 activates YAP1-mediated oncogenic signaling pathways can provide important insights toward cancer metastasis." (PMID 37793774, 2023). "Overall, these reagents’ modulation of YAP1/TAZ subcellular localization represents a promising approach for developing novel cancer therapies." (PMID 37444578, 2023). "In our study, we have also identified KLF5 as a YAP1 tyrosine phosphorylation-dependent interacting transcriptional factor to mediate SRC activation-enhanced cancer stemness and metastasis in TNBCs." (PMID 36633714, 2023). "In in vitro experiments, blockade of YAP1 promoted cancer cell apoptosis, immune cell proliferation, T-cell activation, and cytotoxic T-cell infiltration, thus further potentiating the efficacy of immunotherapy in patients with the SCLC-Y subtype." (PMID 37752152, 2023). "Although studies have shown that Myc is a key molecular target of Yap1 in human cancer, this is the first report in CMs." (PMID 36780463, 2023). "Our findings provide additional evidence for the regulatory effect of m5C modification on YAP1 expression in cancer." (PMID 37537569, 2023). "The secretion of IL-6 by transformed M2 TAMs promotes cancer cells to express more YAP1, K-Ras, β-catenin, NF-κB, and mTOR and thus enhances the percentage of cancer stem-like cells." (PMID 37124519, 2023). "This strengthens the argument that MUC13 is critical in driving cancer aggressiveness and metastasis through the YAP1-dependent oncogenic pathway." (PMID 37793774, 2023). "Further investigation through chemical screening of small-molecule compounds revealed combining MEK inhibitors with YAP1 knockdown significantly improved responsiveness in YAP1-amplified cancer cell lines." (PMID 38067201, 2023). "CircSH3BGRL3 acts as an endogenous sponge for miR-375 to isolate miR-375 and inhibits its activity, increases the expression of its target YAP1, and ultimately activates the Hippo signaling pathway involved in malignant tumor proliferation." (PMID 37397256, 2023). "VP exerts its therapeutic potential against PTX-resistant TNBC by influencing EMT and regulating YAP1, thereby disrupting critical cancer progression pathways." (PMID 38136274, 2023). "To further investigate if YAP1 is downstream to MUC13, in YAP1-mediated survival of cancer cells in an anchorage-independent environment, we knockdown YAP1 expression in ectopic MUC13 expressing (SW480+MUC13) cells." (PMID 37793774, 2023). "CAFs require the YAP1 function to proliferate, migrate, remodel the cytoskeletal machinery and matrix, and promote cancer cell invasion." (PMID 37546745, 2023). "Analysis of actin dynamics in cancer reveals that MET hyperactivation drives perinuclear actin cap disruption by YAP1 inhibition, inducing nuclear expansion, meandering cell motility and collapse of the apical microvilli into actin-rich patches." (PMID 37838732, 2023). "We unveiled a new mechanism by which YAP1 regulates cancer proliferation and metastasis by interacting with HuR." (PMID 37606201, 2023). "As is well known, the YAP1 exert its carcinogenic functions in cancers through the transcriptional activation of target genes in the nucleus." (PMID 37243787, 2023). "YAP1 is a transcription factor downstream of the Hippo pathway, which correlates with a malignant phenotype in cancer." (PMID 37031206, 2023). "VEGFC acts as the upstream of YAP1 in amplification to increase lymphatic density in some malignant tumors." (PMID 37974224, 2023). "Of particular importance, although ΔNp63 was degraded under the exposure of genotoxic substances, interaction with YAP1 to stabilize ΔNp63 protects cancer cells from UV-induced apoptosis." (PMID 37182132, 2023).
cancer (continued). "Yap1 has been reported to crosstalk with NRF2 in cancer development, regulating the susceptibility of cancer cells to ferroptosis." (PMID 37111146, 2023). "Due to insufficient research on circ_0051246, this study aimed to investigate its relationship with miR-375 and YAP1 in cancer stem cells (CSCs)." (PMID 38505381, 2023). "Secondly, studies have suggested YAP1 has a strong impact on the development and maintaining stemness in many cancers." (PMID 37744228, 2023). "P0825 expressed high levels of cancer markers KRT19 and EpCam, cancer stem marker Sox9, Hippo oncogenic co-activator Yap1, and EMT marker Vimentin." (PMID 36865791, 2023). "There is sufficient evidence showing that patients with high nuclear YAP1 in residual cancer after docetaxel‐based chemohormonal therapy have a higher recurrence rate than patients with low nuclear YAP1." (PMID 37799806, 2023). "LncRNA-mediated Hippo/YAP1 pathway regulation has been reported in many cancers and has important roles in cancer progression." (PMID 37537569, 2023). "For example, we have performed high throughput drug screening of FDA-approved drugs and found that zinc pyrithione significantly down-regulates the expression of SDCBP, decreases Hippo/YAP1 pathway activity, and overcomes cancer metastasis." (PMID 37493303, 2023). "Studies have suggested a cooperativity between YAP1 and β-catenin in cancer cell survival via up-regulation of antiapoptotic markers such as BIRC5 and the Bcl2 family of proteins." (PMID 37793774, 2023). "We also evaluated the effects of YAP1 inhibitor treatment combined with chemoimmunotherapy on colony formation and cancer stemness by a colony‐forming assay and flow cytometry." (PMID 37752152, 2023). "Previous research has shown that GPRC5A promotes cancer cell adaptation to hypoxia by activating YAP1, the core protein of the Hippo pathway." (PMID 36735162, 2023). "As a classical transcription activator, YAP1 has been reported to act as an oncogene with a tumorigenic role in developing various cancers." (PMID 37558679, 2023). "This was accompanied by a variation of translocation efficiency of the mechanosensitive co-transcription factor YAP1, albeit with a stronger effect seen for PA and the cancer cells." (PMID 37117602, 2023). "This suggests a central role for YAP-1 in cancer, and thus, it is essential to elucidate how it functions, particularly in response to viral oncogene expression." (PMID 37476371, 2023). "Given the crucial role of the Hippo/YAP1 signaling pathway in cancer metastasis, efforts in drug development are increasingly focusing on targeting this pathway." (PMID 37493303, 2023). "Together, these results demonstrate that ZEB1/YAP1 axis in cancer cells potentially functions downstream of ITGA5/ITGB1 interaction with fibronectin on the surface of fibroblasts." (PMID 36936987, 2023). "Prior work has shown that expression of YAP1 or WWTR1 is detrimental to the viability of NEhi cancer cell lines." (PMID 36719743, 2023). "In brief, the results presented here broaden the significance of MCU13 in cancer metastasis via targeting YAP1 for the first time and provide new avenues for developing novel strategies for targeting cancer metastasis." (PMID 37793774, 2023). "Here, we identified YAP1 as the key downstream substrate of SRC-induced cancer stemness and metastasis in TNBC cells." (PMID 36633714, 2023). "We demonstrate that integrins ITGB1 and ITGA5, which are also upregulated in cancer cells during direct contact with fibroblasts, are involved in YAP1 transcriptional regulation via the CREB pathway." (PMID 36936987, 2023). "BCL2L1, an antiapoptotic factor highly expressed in P4 hESCs, has been shown to be a downstream target of YAP1 in cancer cell models." (PMID 36596852, 2023). "Increased expression and activation of YAP1 have been reported in thyroid cancer cell lines and tissues, making the coiled-coil region of STRNs a potential therapeutic target in cancers with STRN-ALK fusion." (PMID 38201504, 2023).
cancer (continued). "We discovered that LINC02159 was highly correlated with cancer growth and metastasis-related pathways by using transcriptomic analysis and that YAP1 was a potential target gene of LINC02159." (PMID 37537569, 2023). "These previous studies point to the potential utility of YAP-1 as a biomarker for several virally induced cancers." (PMID 37476371, 2023). "We chose 9 genes that were downregulated in LINC02159-knockdown NSCLC cells, including HMGA2, LIN28B, and YAP1, among others, as these genes have been demonstrated to be essential for cancer development and progression." (PMID 37537569, 2023). "Given the importance of MLC-2 in regulating the biomechanical activity of cancer cells, we decided to analyse the effect of RAR-β activation on the expression of YAP-1, a well-known marker of mechanically active cancer cells." (PMID 37130839, 2023). "YAP-1 expression was significantly higher in poorly and moderately differentiated invasive squamous cancer than in well-differentiated carcinomas." (PMID 37476371, 2023). "Intriguingly, we found that the expression of YAP1 was positively correlated with the expression of MKI67 in most of the cancer types." (PMID 35685435, 2022). "To assess the role of YAP1 in predicating clinical outcomes of patients in 33 cancer types, we analyzed OS, DSS, DFI, and PFI using the Kaplan–Meier method (log-rank test) and univariate Cox regression." (PMID 36479120, 2022). "Having observed that most of the circRNAs reviewed in this paper exert their functions by targeting YAP1 in cancer, this highlights potential roles for these circRNAs in transcriptional control as well." (PMID 35673576, 2022). "YAP1 subsequently binds to the enhancer region of PD-L1 and stimulates transcription activity, increasing PD-L1 levels in cancer cells." (PMID 36499561, 2022). "By single-cell RNA-seq analysis of data provided by Stanford Medicine, YAP1 was found predominantly expressed in cancer cells, fibroblasts, and endothelial cells, while TAZ expression was diffusely distributed with slightly higher expression in T cells." (PMID 36289774, 2022). "YAP1 promotes cancer development in a variety of ways, including promoting a malignant phenotype, expansion of cancer stem cells, and cancer cell resistance." (PMID 34974798, 2022). "For example, YAP1, a transcription co-activator whose activation is important for cancer cell proliferation, survival, migration and invasion, is one of the critical targets that mediate ALKBH5’s function in multiple cancers." (PMID 35063010, 2022). "According to the results from the TIMER database, YAP1 exhibited inconsistent mRNA expression in 33 types of common cancers." (PMID 35685435, 2022). "Consistent with the CRISPR KO results, the inhibition of the YAP1 transcriptional co-activating function by the specific compound CA3 resulted in cell death in 11q22.1 amplified/silent cancer cell lines and normal controls as well." (PMID 34997070, 2022). "In our integrative pan-cancer analysis, the results showed that overexpression of YAP1 only predicted poor prognosis in PAAD and LGG, which was inconsistent with the reported that YAP overexpression predicted worse OS in LIHC, ESCA, BLCA, and BRCA." (PMID 35685435, 2022). "Clinical data from various cancer types were analyzed to reveal relationships among YAP1, OCT4, and CDH6 in MSC--involved tumorigenicity." (PMID 35356283, 2022). "Hippo pathway components are indispensable during development, whereas, the Hippo pathway effector protein, YAP1, contributes to the genesis and progression of various cancers." (PMID 35937460, 2022). "Further analyses showed that YAP1 expression was positively correlated to a wide range of immune checkpoints, especially in PAAD, PCPG, and PRAD, suggesting that YAP1 is a potential new drug target for anti-cancer immunotherapy in these cancer types." (PMID 36479120, 2022). "YAP1 is expected to become a new target for the treatment of malignant tumors of the digestive system." (PMID 35911146, 2022).